MMP9 (matrix metallopeptidase 9)
Diseases named in the same sentence as MMP9 in open-access papers (continued):
Sharing a sentence is not in itself a finding about the gene and the disease.
Stroke (continued). "Among MMPs, uncontrolled MMP-9 expression and activity lead to the pathological effects of brain disorders, such as stroke, brain tumor, and AD." (PMID 30562971, 2018). "tPA expression and activity in the healthy human cortex have been reported earlier and MMP-2 and MMP-9 activities have been studied in the ischemic core of stroke patients." (PMID 28290150, 2018). "One study shows that, via stabilizing MKP-1, IRAK-M can suppress p38 activation, while p38 activation can lead to MMP-9 increase in astrocytes, composing a possibility that p38 activation in IRAK-M-null mice upregulates MMP-9 in the experimental stroke." (PMID 30622459, 2018). "Inhibition of MMP-9, the primary MMP implicated in stroke-induced neuroinflammation and the biphasic disruption of the blood–brain barrier, has shown mixed results in experimental studies depending on the timing of administration." (PMID 29752550, 2018). "In our study, the activity of tPA and MMP-9 is increased in the ipsilateral somatosensory cortex of the stroke EE group compared to the stroke STD group." (PMID 28290150, 2018). "In the early phase of stroke, MMP-9 damages the blood–brain barrier (BBB) and contributes to vasogenic edema, whereas in later stages, it contributes to remodeling around the peri-infarct areas, and consequently targeting MMP-9 at this time can be harmful." (PMID 29930530, 2018). "The neuronal activity-regulated protease Mmp-9 plays an important role in synaptic plasticity, learning, and memory as well as in many central nervous system (CNS) diseases, including stroke, epilepsy, schizophrenia, neurodegenerative disorders, and so on." (PMID 29686606, 2018). "Increased MMP9 expression in the acute phase of stroke in DM patients creates a pro-inflammatory state that worsens WM damage." (PMID 29896433, 2018). "In DM stroke patients, microglial activation is increased within minutes of ischemia onset and triggers the production of inflammatory cytokines, including MMP9 and TNFα, which exacerbate tissue damage." (PMID 29221142, 2017). "The increased plasma MMP-9 level and the presence of MMP-9 in human brain sections after both ischemic and hemorrhagic stroke further support a role for MMP-9 in the pathophysiology of stroke." (PMID 28115020, 2017). "Matrix metalloproteinase-9-deficient mice had smaller infarcts following tMCAO, and chimeric studies showed that MMP-9 expressed particularly by leukocytes contributed to worsened stroke outcome." (PMID 28936196, 2017). "Matrix metallopeptidase 9 (MMP-9), for example, not only exacerbates brain damage in the early phase after stroke but also contributes to neurovascular remodeling and promotes poststroke recovery by converting pro-VEGF into an active form." (PMID 28824617, 2017). "TIMP-1 overexpression also ameliorates MMP-9 mediated blood-brain barrier leakage in models of stroke, traumatic brain injury and cerebral ischemia." (PMID 29459817, 2017). "For example, S1PR2 expression has been reported in brain endothelial cells and its activity increased MMP-9 activity and promoted blood-brain barrier permeability during stroke." (PMID 28725183, 2017). "Although prolonged inhibition of MMP-9 was found to be detrimental to the late recovery phase of stroke." (PMID 28115020, 2017). "Treatment with MMP-9 inhibitor within 24 h of stroke reduced infarct size at day 14, and this benefit was lost when the treatment was delayed until 72 h." (PMID 28115020, 2017). "Clinical studies showed that serum MMP-9 levels correlated with stroke severity, with MMP-9 mRNA as a predictor of poor outcome." (PMID 28936196, 2017). "One such study in support of the neutrophil-derived MMP-9 theory was carried out in rats with neutropenia treatment prior to induction of stroke to deplete neutrophils." (PMID 26973468, 2016). "Such elevated TIMP-1 expression was observed in conjunction with elevated MMP-9 levels at 24 h following stroke onset." (PMID 26973468, 2016).
Stroke (continued). "In ischemic stroke patients, a correlation between plasma MMP-9 levels and final National Institute of Health Stroke Scale (NIHSS) score, which is used to objectively quantify the impairment cause be stroke, has been observed." (PMID 26973468, 2016). "In contrast, gelatinase B/MMP-9 activity, the predominant mechanism previously thought to mediate post-stroke BBB disruption, contributes to leakage of larger macromolecules (⩾40 kDa) across the BBB in a relatively delayed manner (after more than 3 h)." (PMID 26813496, 2016). "Without reperfusion, candesartan administration had the opposite effect and significantly reduced both MMP2 and MMP9 activity after stroke." (PMID 27127602, 2016). "In keeping with the experimental literature, studies of clinical stroke patients have revealed increased levels of MMP-9 following ischemic stroke in humans with elevated MMP-9 levels observed compared to healthy controls." (PMID 26973468, 2016). "In this way, MMP-9 is proposed as a marker for ongoing brain ischemia and evolution of the stroke lesion, making it a potential candidate for inclusion in a stroke biomarker panel." (PMID 26973468, 2016). "Gene expression analysis of peripheral blood taken from ischemic stroke patients revealed that MMP-9 was significantly upregulated in neutrophils early after stroke." (PMID 26973468, 2016). "A number of studies have sought to investigate what cells are releasing MMP-9 in stroke, with both peripheral and central candidates examined." (PMID 26973468, 2016). "This is the first report to show that 2-week low-frequency rTMS increases serum levels of mature BDNF and MMP-9 in stroke patients." (PMID 27007747, 2016). "An increase of MMP-9 has failed though as a single marker of stroke and yet a panel of biomarkers showed sensitivity and specificity on the level of approximately 90%." (PMID 28104930, 2016). "In this study, we found that an increase of biochemical markers as BNP, D-Dimers, MMP-9, S and 100β tested with a Triage Stroke Panel (>4) was correlated with mortality at 120 days from stroke onset." (PMID 27247610, 2016). "Early after stroke (12–48 h) neutrophils adhere to the cerebrovascular endothelium where they release MMP-9 that degrades the basal lamina of the endothelial cells and astrocytes." (PMID 26973468, 2016). "In contrast, when neutrophils are increased via lipopolysaccharide or granulocyte colony-stimulating factor administration, there is an increase in BBB disruption in a mice model and an increase in MMP-9 and rtPA-related HT in a rat stroke model." (PMID 27561990, 2016). "Numerous clinical and experimental studies have confirmed an increase in serum MMP-9 following stroke." (PMID 26973468, 2016). "At least 23 MMPs have been identified to date, with MMP-2 and MMP-9 the most widely studied in stroke." (PMID 26973468, 2016). "Neutropenia treatment prior to stroke markedly reduced MMP-9 expression and prevented infiltration of neutrophils into the ischemia tissue." (PMID 26973468, 2016). "A wide range of cell types have been shown to express MMP-9 following stroke, including neurons, microglia, and endothelial cells." (PMID 26973468, 2016). "In particular, MMP-9 has been implicated, not only in the pathogenesis of BBB breakdown and subsequent vasogenic edema formation following stroke, but also in hemorrhagic transformation (HT) in the setting of tissue plasminogen activator (tPA) therapy." (PMID 26973468, 2016). "MMP-9 levels in ischemic stroke patients were significantly elevated at 7d compared to 1d post-stroke, with a temporal profile study out to 12d post-stroke revealing that levels of MMP-9 increased steadily over time following the onset of cerebral ischemia." (PMID 26973468, 2016). "This increase of nuclear gelatinolytic activity of MMP-2 and/or MMP-9 was also observed in human brain after stroke." (PMID 26925194, 2016).
Stroke (continued). "In stroke an increase of MMP-9 is regarded to be a marker of increased blood-brain barrier permeability and hemorrhagic transformation of ischemic foci." (PMID 28104930, 2016). "As has been observed in the experimental stroke literature, MMP-9 levels increase over time following clinical stroke." (PMID 26973468, 2016). "An increase of biochemical markers such as BNP, D-Dimers, MMP-9, and S100β tested with a Triage Stroke Panel (>4) was correlated with mortality at 120 days from stroke onset." (PMID 27247610, 2016). "Gene expression studies of peripheral blood from stroke patients reveled that MMP-9 was one of the key genes upregulated in response to stroke." (PMID 26973468, 2016). "MMP-9 knockout significantly attenuates leukocyte recruitment into brain tissue following stroke, implicating a pro-inflammatory role for MMP-9 in the recruitment of leukocytes to reperfused brain tissue." (PMID 26973468, 2016). "This poor outcome and increased levels of MMP-9 were subsequently correlated with both infarct volume and stroke severity." (PMID 26973468, 2016). "Cerebral MMP-9 expression has been found to increase in the early hours after stroke onset and MMP-9 is thought to be a mediator of increased blood–brain barrier permeability and hemorrhagic transformation following ischemic stroke." (PMID 27247610, 2016). "Expression of matrix metalloproteinase (MMP) in healthy brain is relatively low, but activated MMPs, especially MMP-2 and MMP-9, increase during stroke, which leads to disruption of blood brain barrier (BBB) integrity and contributes to brain edema." (PMID 25914628, 2015). "The MMP-9 activity was markedly increased from days 2 to 14 after stroke, whereas a significantly smaller increase in MMP-2 activity was observed compared with MMP-9 activity." (PMID 26581247, 2015). "Altogether these data indicate that S1PR2 plays a critical role in MMP-9 activation and the induction of gelatinase activity in cerebral microvessels after I/R injury in experimental stroke." (PMID 26243335, 2015). "The expression of arginase 1 (expressed by monocytic MDSCs), S100A9 (induces generation and expansion of MDSCs), and MMP-9 (secreted by MDSCs), were found to be amongst the genes that showed the highest increase in expression post-stroke." (PMID 26690125, 2015). "The high levels of MMP-9 in acute ischemic stroke confirm the involvement of this metalloproteinase in the regulation of inflammation in stroke." (PMID 26330106, 2015). "MMP-2 is responsible for early BBB disruption, while MMP-9 is involved in brain injury at relatively late stroke stages in vivo and in vitro." (PMID 25815722, 2015). "Recent studies reported increased enzymatic MMP9 activity within 24 h after a PT-stroke, and application of a broad spectrum MMP-inhibitor (FN-439) applied at the time of stroke induction, partially rescued impaired barrel cortex plasticity." (PMID 26609811, 2015). "An association between MMP9/TIMP1 ratio and the most severe ischemic stroke subtype was found in a cohort of 126 untreated stroke patients." (PMID 26074872, 2015). "Accumulated evidence suggests that MMP-9 activation is closely related to BBB disruption after stroke." (PMID 26537366, 2015). "Further, intracellular MMP-2 and MMP-9 are complicit in neuronal apoptosis in both in vitro and in vivo stroke models." (PMID 26588897, 2015). "Excessive MMP-9 activity is known to be involved in brain injury such as stroke, and exacerbates neuronal apoptosis and impairment of neurovasculature." (PMID 25859655, 2015). "Consistent with Western blot analysis, results from this assay verified that apelin-13-treated animals showed enhanced activity of MMP9, compared with those in stroke control animals 14 days after stroke." (PMID 26391329, 2015). "Several reports have shown that serum levels of MMP-9 increase in the acute phase of stroke and MMP-2 levels increase after several days." (PMID 26330106, 2015).
Stroke (continued). "There is evidence that diabetic obesity is associated with both vascular impairment and neurodegenerative conditions, and MMP-9 upregulation in diabetic mice exacerbates white matter damage after stroke." (PMID 25859655, 2015). "In the adult rodent brain, neuroprotection afforded by the inhibition of MMP-9 activation has previously been demonstrated after focal cerebral ischemia, stroke, and TBI, either by using MMP-9-deficient animals or pharmacological inhibition." (PMID 26588471, 2015). "Two specific MMPs, MMP-2 (gelatinase A) and MMP-9 (gelatinase B), have been the subjects of extensive studies in the stroke field." (PMID 25925889, 2015). "Among MMPs, MMP-9 has been most intensively studied for its involvement in BBB disruption after stroke." (PMID 26012470, 2015). "MMP-2 is constitutively expressed at low levels in normal brain tissue; however stroke increases its expression and activity and also induces the expression of MMP-9." (PMID 24579051, 2014). "Disruption of the blood-brain barrier following stroke is commonly associated with the action of two matrix metalloproteinases, MMP-2 and MMP-9." (PMID 24579051, 2014). "We showed that engrafted hNSCs significantly reduced the stroke-induced elevated MMP-9 level 48 hours post-MCAO/R, suggesting that hNSCs can ameliorate BBB disruption by inhibiting the elevated enzyme’s associated harmful events." (PMID 25418536, 2014). "It is well known that matrix metalloproteinase (MMP) activation, in particular MMP2 and MMP9, is a critical mediator of hemorrhagic transformation after aneurysm formation and stroke." (PMID 24991237, 2014). "One marker for BBB permeability is MMP-9 and studies have shown that MMP-9 is responsible for rt-PA induced parenchymal hemorrhages after stroke." (PMID 24465746, 2014). "Several studies have demonstrated that MMP-9 plays an important role in BBB disruption after stroke." (PMID 24739149, 2014). "miR-320 targets ETS2, a transcription factor that regulates the expression of several genes important to leukocyte extravasation post-stroke including MMP-9, MMP-3, MMP-13, ANGPT1, and TNF." (PMID 24911610, 2014). "Hyperbaric oxygen treatment improved BBB function in a rat embolic stroke model through modulation of MMP-9 but displayed reduced effectiveness when administered in combination with tPA." (PMID 24579051, 2014). "Clinical studies have shown a correlation between plasma MMP-9 levels and the rate of HT in human stroke." (PMID 23565108, 2013). "MMP-9 breaks down the collagenase matrix near cerebral blood vessels following a stroke, which, in conjunction with elevated inflammatory markers, augments BBB disruption." (PMID 23344061, 2013). "tPA therapy independently predicted hyperacute plasma MMP-9 after adjustment for stroke severity, volume, and HT in the first 8 h after human ischemic stroke." (PMID 23565108, 2013). "High plasma MMP-9 concentrations in the acute phase of a cerebral infarction is considered to be independent predictor of HT in all stroke subtypes." (PMID 23565108, 2013). "MMP-9 level was significantly increased after stroke onset, with the level correlating with infarct volume, stroke severity, and functional outcome." (PMID 23565108, 2013). "We found that combination treatment of stroke in T1DM rats significantly decreased MMP9 and Angiogenin expression compared to BMSC monotherapy or T1DM-control groups." (PMID 24303036, 2013). "Studies in experimental animal models and stroke patients strongly suggest that MMP-9 plays a central role in tPA-mediated neurotoxicity from thrombolytic therapy for acute stroke." (PMID 23565108, 2013). "A recent clinical trial indicates that minocycline can lower plasma MMP-9 levels, even at 72 h after stroke, and improve neurological outcomes in acute ischemic stroke patients treated with tPA." (PMID 23565108, 2013).
Stroke (continued). "From clinical perspective, the results gain importance especially when TIMP-1 and MMP-9 together are recently under intense investigation as a biomarker for stroke and cardiovascular death in humans." (PMID 24146955, 2013). "In adult stroke patients undergoing t-PA thrombolysis and in animal models of ischemia, t-PA up-regulated plasma levels or brain MMP-9, while levels were reduced in t-PA knockout mice." (PMID 23940734, 2013). "Inhibition of MMP-9 during the late phase (7–14 days) after stroke has been shown to reduce the number of neurons and new vessels, and that correlated with increased brain injury and impaired functional recovery." (PMID 23565108, 2013). "MMPs have been thought to be involved in stroke pathogenesis and clinical reports indicated elevated serum level of MMP-9 among patients with ischemic stroke." (PMID 24288462, 2013). "Recently, it was shown that MMP-9 mRNA concentration was almost three times higher in non-survival patients compared to survival patients with acute stroke; therefore, MMP-9 mRNA was a predictor of poor outcome and mortality in stroke." (PMID 23565108, 2013). "A recent review of the literature concerning MMP-9 and stroke suggests that MMP-9 is a possible marker for acute ischemic stroke." (PMID 23565108, 2013). "In contrast, an increase in plasma MMP-9 was observed later (at day 7) and related to more severe stroke." (PMID 23565108, 2013). "There are temporal and spatial changes of MMP-9 within the cells of the neurovascular unit after stroke." (PMID 23565108, 2013). "Our findings that MMP-9 levels were reduced in EphA2−/− mice are consistent with their milder post-stroke BBB damage and subsequent leakage, as compared to WT counterparts." (PMID 23308246, 2013). "We further investigated mechanisms related to damage of the BBB cellular matrix after stroke by evaluating the levels of matrix metalloproteinase-9 (MMP-9)." (PMID 23308246, 2013). "This review revealed that higher MMP-9 values were significantly correlated with larger infarct volume, severity of stroke, and worse functional outcome." (PMID 23565108, 2013). "In particular, MMP-9 activity is significantly elevated in human brain tissue and serum after stroke as well as in animal stroke models beginning at 12 h after permanent MCAO." (PMID 23565108, 2013). "This is consistent with other findings that suggest that inhibition of MMP9 attenuates neuroinflammation and promotes recovery after stroke." (PMID 24303036, 2013). "In stroke, MMP-9 plays a principal role in hemorrhagic conversion and vasogenic edema in animal models and stroke patients." (PMID 23522154, 2013). "A recent clinical trial indicated that minocycline can lower plasma MMP-9 levels, even at 72 hours after stroke, and improve neurological outcomes in acute ischemic stroke patients treated with tPA." (PMID 22587708, 2012). "They designed an ischemic-reperfusion rat model, with a 90 min middle artery occlusion, and also used tissue from stroke patients to investigate the role of MMP-9 in ischemic brain neurons." (PMID 23110201, 2012). "This lag of time explains the missing difference between the group of ischemic strokes and stroke imitating diseases for S100 B and MMP-9 in our cohort most likely." (PMID 22400994, 2012). "This view is supported by former studies showing an attenuated MMP-9 upregulation after experimental stroke treated with hyperoxia." (PMID 22273146, 2012). "In this regard, MMP-9 null mice have been found to be less afflicted than wild-type mice by EAE and stroke, whereas MMP-9 and MMP-12 null mice recover better from spinal cord injury." (PMID 22567285, 2012). "This increase in MMP-9 was confirmed with positive immunofluoresence staining for MMP-9 within the ipsilateral stroke hemisphere and corresponding reductions of such staining with hypothermia." (PMID 22742423, 2012).